BCL2 (BCL2 apoptosis regulator)
Diseases named in the same sentence as BCL2 in open-access papers (continued):
Sharing a sentence is not in itself a finding about the gene and the disease.
melanoma (continued). "We previously demonstrated that, in addition to its canonical anti-apoptotic role, Bcl-2 is involved in multiple non-canonical functions, including melanoma metastasis, angiogenesis, and autophagy." (PMID 30454024, 2018). "Similarly, with the up-regulation of cleaved-caspases-3 and down-regulation of Bcl-2, CPT induced apoptosis in melanoma cells and colorectal cancer cell lines." (PMID 28654902, 2017). "In present study, we attempt to investigate the anti-cancer mechanisms of piceatannol in the highly aggressive human melanoma cell line, WM266-4 and A2058, and elucidate the inhibitory effect of piceatannol on melanoma cells through attenuating miRNA-mediated Bcl-2." (PMID 29041990, 2017). "Our results indicated that combination inhibition of BCL-2 and DHODH might be a new therapeutic regimen for malignant melanoma treatment." (PMID 29348830, 2017). "Several Bcl2 proteins are downstream of commonly activated RAS/BRAF/MAPK and PI3K/Akt signaling pathways which play an important role in tumor initiation and maintenance of melanoma specific CSCs compartment." (PMID 28137308, 2017). "These JARID1b-high cells in melanomas do not show differences in the expression of genes related to cell survival such as Bcl-2, but they accumulate proteins related to mitochondrial activity." (PMID 28562344, 2017). "We show that cross talk between melanoma cells, macrophages, and fibroblasts initiates an IL-1 signaling cascade that generates a CXCR2-stimulating secretome, which ultimately leads to enhanced melanoma cell survival in the presence of MAPK signaling inhibition, via BCL2 up-regulation." (PMID 28450382, 2017). "BCL2 over-expression blocked the effects of digitoxin plus MEK inhibitor on melanoma cell death but did not rescue the effects on intracellular acidification." (PMID 27545456, 2016). "Cell death appeared to occur by apoptosis as digitoxin plus MEK inhibitor significantly increased the number of activated caspase-3+ cells in control and tRFP-expressing melanomas, but not in BCL2 over-expressing melanomas." (PMID 27545456, 2016). "Therefore, melanoma and EGFR-modified glioblastoma cell lines provide diverse contexts to test the BCL2-profiling capacity of the designed proteins." (PMID 27805565, 2016). "However, the expression of Bcl2 was decreased by the treatment of IL-4 in SK-MEL-28 and B16F10 melanoma cells." (PMID 26993600, 2016). "Wellbrock and coworkers proposed that a low basal MITF level could be important for the survival of melanoma cells and also for their proliferation through regulation of cyclin-dependent kinase 2 (CDK2) and B-cell CLL/lymphoma 2 (BCL2)." (PMID 26927636, 2016). "BCL-2 inhibitors have been successful in treatment of chronic lymphocytic leukemia, but not in melanoma due to high expression of anti-apoptotic proteins such as MCL-1." (PMID 27829238, 2016). "AZD6244-BEZ235, but not PLX4720-BEZ235, downmodulated the anti-apoptotic gene Bcl-2 and the mTOR interactor 4EBP1, as well as β catenin, a gene that impairs T cell-mediated immune response in melanoma, and LEF-1 a β catenin interacting partner." (PMID 26678033, 2016). "In line with our results, the co-overexpression of BCL-2 and β-catenin has been reported in other tumors and the transcriptional regulation of BCL-2 by MITF has been documented in primary melanocytes and melanoma cells." (PMID 27175588, 2016). "BCL2 is a MITF target gene involved in melanocyte and melanoma cell proliferation and survival." (PMID 26116372, 2015). "The level of BCL-2 protein was not markedly altered during response of melanoma cells to changes in the medium composition." (PMID 26035829, 2015). "At the molecular level, VS-5584 blocked AKT-mTOR activation and downregulated cyclin D1 expression in melanoma cells, while the expressions of Bcl-xL and Bcl-2 were not affected by VS-5584 treatment." (PMID 26204252, 2015). "Additionally, Bcl-2 inhibitors, such as ABT-737 and obatoclax, induce ER stress in human melanoma cells." (PMID 26506422, 2015).
melanoma (continued). "Above results have shown that expressions of Bcl-xL and Bcl-2 were not affected by the VS-5584 treatment in melanoma cells." (PMID 26204252, 2015). "This delay in effect is concordant with prior data generated in human melanoma lines in which BCL-2 was not down regulated until 32 hours following exposure to SINE compounds." (PMID 25022346, 2014). "Although ABT-737 is the most potent and selective small-molecule Bcl-2 inhibitor, it is not very effective against cancer cells that harbor high levels of Mcl-1, such as breast, lung, and melanoma cells." (PMID 24223823, 2013). "Our results on the down-regulation of Bcl-2 and PCNA expression were further supported by flow cytometric cell cycle analyses of curcumin-treated B78H1 cells, indicating that curcumin affects both apoptosis and proliferation of this melanoma cell line." (PMID 24349037, 2013). "We investigated the extent to which Mcl-1 affects the sensitivity of melanoma cells to ABT-737 and thus whether combination therapy targeting Mcl-1 and Bcl-2 has a promise in the context of melanoma." (PMID 24223823, 2013). "To investigate the mechanism underlying CACF-induced cell death, we performed Western blotting to examine the expression level of Bcl-2 in human melanoma cells with/without CACF treatment for 24 h." (PMID 23837445, 2013). "As observed in our study, melanocytes express high levels of Bcl-2 compared to other cell types of the skin and no increase in Bcl-2 expression was observed when melanocytes were compared with melanoma cells." (PMID 22292048, 2012). "It was found that melanoma cell lines – in contrast to non-malignant fibroblasts - required specific antiapoptotic Bcl-2 proteins for survival." (PMID 22292048, 2012). "In this study, we systematically investigated the relevance of antiapoptotic Bcl-2 proteins, i.e., Bcl-2, Bcl-xL, Bcl-w, Mcl-1, and A1, in melanoma cell lines and non-malignant cells using RNAi." (PMID 22292048, 2012). "Overall, no general increase in the expression of antiapoptotic Bcl-2 proteins was observed in melanoma cell lines, which would point towards a pro-survival role." (PMID 22292048, 2012). "A consistent, but not significant increase was also observed when Bcl-2, Bcl-xL, and Bcl-w were targeted in 1205Lu melanoma cells." (PMID 22292048, 2012). "This hypothesis is strengthened by other data showing that the silencing of Bcl2, FLIP or IAPs (XIAP and survivine) by siRNAs sensitizes resistant melanoma cells to TRAIL-induced apoptosis." (PMID 22136382, 2011). "We previously found that resistance to ABT-737 in melanoma cells is mediated by the anti-apoptotic Bcl-2 member Mcl-1, which ABT-737 does not inhibit." (PMID 21897876, 2011). "In the case of 1H3 T-cells, destruction of A02 melanoma cells was mediated almost exclusively via the perforin/granzyme-B system, either in the presence or absence of the Bcl-2 inhibitor." (PMID 17311012, 2007). "The different patterns of Fas and Bcl-2 expression in TIL-2 from colon carcinomas and melanomas could be attributed to different homeostatic conditions in rapidly expanding cell cultures since these two markers are apoptosis related." (PMID 12610520, 2003). "Our findings show for the first time that pamidronate has a direct effect on melanoma cells, which is not blocked by overexpression of bcl-2." (PMID 12177810, 2002). "However, Bcl-2 family modulation varies across cancers: fucoxanthin reduces Bcl-xL in melanoma but spares it in PC-3 prostate cancer, while HL-60 cells show no Bcl-2/Bcl-xL/Bax changes." (PMID 40735485, 2025).
melanoma (continued). "The exogenous H2S donor, NaHS, amplifies the apoptotic process in melanoma A375 and SK-MEL-282 cells, demonstrating the antitumor effect of H2S treatment at high concentrations (via suppression of the PI3K/AKT/mTOR, NF-KB, AKT, ERK1/2, MAPK/ERK, PI3K/Akt pathways, FLIP, XIAP, Bcl-2, PHLDA genes)." (PMID 41373571, 2025). "In melanoma, PTBP1‐mediated splicing of the lncRNA LHFPL3‐AS1 precursor produces the lncRNA LHFPL3‐AS1‐long that inhibits the degradation of its target gene, Bcl‐2 mRNA, and upregulates the expression of Bcl‐2 by acting on miR‐181, which inhibits apoptosis and promotes melanoma stem cell death." (PMID 40579921, 2025). "The use of CM from Bcl-2 overexpressing melanoma cells treated with the specific YAP inhibitor Verteporfin, reduced in vitro fibroblasts migration, and both α-SMA protein level and ERK phosphorylation, indicating the involvement of YAP in fibroblast activation by cancer-specific Bcl-2." (PMID 38755629, 2024). "On the basis of these results evidencing the Bcl-2 regulation of Hippo pathway and stiffness, and considering our previous data demonstrating the involvement of melanoma-specific Bcl-2 in the TME, we investigated whether Bcl-2 could promote fibroblast activation." (PMID 38755629, 2024). "Targeting BCL‐xL‐/BCL‐2 could sensitize tumour‐resistant cells to EGFR inhibitors, or result in the inhibition of actin remodelling molecules counteracting adaptive resistance to BRAF inhibitors in melanoma." (PMID 38693863, 2024). "In addition, immunofluorescence assays revealed a reduction in MITF following Bcl-2 overexpression, suggesting that Bcl-2 may be a regulator of MITF in the context of melanoma." (PMID 39594467, 2024). "Interestingly, in both melanoma models, also MOB1 was found decreased after Bcl-2 overexpression." (PMID 38755629, 2024). "In both 2D cell models and 3D-PCS-PDMEs, LMW-F showed the ability to inhibit the proliferation of melanoma cells by affecting apoptosis-related factors such as PTEN/AKT signaling pathways, caspase-3 activity, and Bcl-2 phosphorylation at Thr56, as well as by reducing Bcl-2 and H2B expression." (PMID 38186578, 2023). "Preclinical evidence in melanoma demonstrated its ability to induce anoikis and suppress metastasis in human melanoma cells, interrupting ECM attachment and FAK phosphorylation, and resulting in caspase activation through a decrease in the Bcl-2/Bax protein ratio." (PMID 37181747, 2023). "Trametinib-resistant melanoma cells grown with or without trametinib did not respond with substantial apoptotic death to ABT-263 or ABT-199 in our study indicating that these cells did not rely on anti-apoptotic proteins BCL-2, BCL-XL, and/or BCL-w." (PMID 37835493, 2023). "Thus, BH3 mimetics for targeting Bcl-2, Bcl-xL, and Bcl-w (ABT-737, -263, -199) have been developed, and their combination with vemurafenib has resulted in enhanced apoptosis and reduced cell viability in BRAF-mutant melanoma cells." (PMID 36902392, 2023). "In melanoma, a recent paper unveiled a regulatory circuit centered on the lncRNA LHFPL3-AS1 (LHFPL3 Antisense RNA 1): by sequestering miR-181a-5p, it positively affects the expression of BCL2 (B-cell lymphoma 2), thus inhibiting the apoptosis of melanoma cells, and in particular melanoma stem cells." (PMID 36768150, 2023). "The increase in Bax expression and decrease in Bcl2 expression was again lower in the tumor tissues of CD133+-injected mice than in other two groups (unsorted and CD133), which might indicate the greater resistance of CD133+ melanoma cells to apoptosis." (PMID 36325671, 2022). "Furthermore, targeting CRAF in a variety of melanoma cell lines was shown to decrease their viability, which appears to be mediated by Bcl-2 inhibition, rather than MAPK inhibition." (PMID 35883461, 2022).
melanoma (continued). "CD133 overexpression in BAKR cells also correlates with the dramatic upregulation of basal levels of anti-apoptotic BCL-2 and down-regulation of the pro-apoptotic BAX protein which may tilt the balance towards increased cell survival upon treatment with targeted melanoma therapeutics." (PMID 35216449, 2022). "Notably, combinations targeting both MCL-1 and BCL-2 (e.g., S63845 and Venetoclax) have proven efficacious and safe in clinical trials in both haematological (e.g., AML, T-cell ALL, MCL) and solid cancers (e.g., melanoma)." (PMID 33799592, 2021). "Hence, we reasoned that co-inhibition of BCL2 and MCL1 in nf1/pten-mutant melanoma cells might produce an even greater synergistic antitumor effect than observed with either inhibitor given individually with sirolimus." (PMID 34331013, 2021). "A human A375 cell line melanoma xenograft murine model has shown that deletion of glucose-6-phosphate dehydrogenase (G6PD), which catalyzes the pentose-phosphate pathway, upregulates the antiapoptosis proteins Bcl-2 and Bcl-xL, whereas the tumor suppressor, Fas, was shown to be downregulated." (PMID 34067095, 2021). "Altogether, our results indicate that the elevated expression of BCL2L10 in melanoma contributes to cell survival upon treatment with different cytotoxic compounds, making BCL2L10 a promising target in the context of inhibiting anti-apoptotic Bcl-2 proteins in malignant melanoma treatment." (PMID 33396645, 2020). "Hence, melanoma cells are not exclusively dependent on BCL-2, BCL-XL, or MCL-1 for survival, nor does co-targeting BCL-2, BCL-XL and BCL-W cause significant melanoma cell killing." (PMID 31019203, 2019). "Bid may antagonize Bcl-2; however, this was apparently not sufficient for apoptosis induction in resistant melanoma cells." (PMID 31083589, 2019). "Hence, BCL-XL, BCL-2 and MCL-1 are all potential clinically-relevant targets in melanoma." (PMID 31019203, 2019). "In melanoma and other tumors, resistance to kinase inhibitors like BRAFi and MEKi is often mediated by an abrogation of intrinsic apoptosis signaling pathways—namely by downregulation of BH3-only proteins or by induction and activation of BCL-2 family members like BCL-2, BCL-XL, BFL-1, and MCL-1." (PMID 29794999, 2018). "Here we examined whether combining a GSI (γ-Secretase Inhibitor) with ABT-737 (a small molecule BCL-2/BCL-XL/BCL-W inhibitor) can kill both the non-MICs (bulk of melanoma) and MICs." (PMID 27829238, 2016). "Western blots showed 100μM propranolol significantly reduced the expression of Bcl-2 while increasing the expressions of Bax, cytochrome c, cleaved capase-9 and cleaved caspase-3, and down-regulated the levels of p-AKT, p-BRAF, p-MEK1/2 and p-ERK1/2 in melanoma cells, after a 24h incubation." (PMID 27582542, 2016). "We observed that treatment of melanoma cells with BRAF inhibitors did not induce Bcl-2 expression." (PMID 26497853, 2015). "VS-5584 failed to affected Bcl-xL and Bcl-2 expressions in tested melanoma cells." (PMID 26204252, 2015). "There are different mechanisms and pathways responsible for anti-melanoma actions of medicinal compounds such as promotion of caspase activity, inhibition of angiogenesis and inhibition of the effects of tumor promoting proteins such as PI3-K, Bcl-2, STAT3 and MMPs." (PMID 25102117, 2014). "Attempts to target BCL2 with antisense RNA in melanoma patients have not been successful." (PMID 24743024, 2014). "Therefore, Bcl-2 and Bax family proteins modulate melanoma proliferation through PI3K/mTOR or MAPK signaling pathways and could effectively regulate melanoma disease and prevent tumor progression." (PMID 24647338, 2014).
melanoma (continued). "Our data would predict that a similar differential imbalance between pro (Bax)-/anti (Bcl-2, Bcl-xL, Mcl-1, Xiap)-apoptotic proteins is likely to occur within the subset of TAA-specific (but not bulk or viral-specific) CD4+ T cells in the peripheral blood of melanoma or RCC patients with AD." (PMID 25325015, 2014). "In the melanoma tumor tissues of the CCR5−/− mice, the expression of NF-κB target cell death genes (Bax, caspase-3 and 9) and the DNA binding activity of NF-κB, were significantly inhibited, but the expression of cell death inhibitory NF-κB target genes, such as Bcl-2 and cIAP were enhanced." (PMID 22567084, 2012). "In addition, non-malignant cells were analyzed in order to dissect Bcl-2 proteins that are specifically important for melanoma survival." (PMID 22292048, 2012). "Interestingly, in accordance with these observations, our result demonstrate that the integration of DDP with bcl-2 ASO and EP produced an impressive antitumor efficacy on this melanoma model, suggesting a possible translational application of this therapeutic strategy." (PMID 21798045, 2011). "Since Bcl2 expression was lower in metastatic melanoma than in benign nevi and Bclxl and Mcl-1 were overexpressed in metastatic melanoma, Bcl2 may not be an optimal anti-apoptotic protein to target in melanoma." (PMID 24281185, 2010). "In melanoma, the apoptotic action of nitrogen-containing bisphosphonates involves caspase-3 activation and is not influenced by bcl-2 overexpression." (PMID 15280922, 2004). "Thus, melanoma cells were not addicted to BCL2 for viability when the ERK1/2 pathway was inhibited." (PMID 31727888, 2019). "Overall, by affecting the expression levels of both KIT and BCL-2 proteins and, consequently, by impinging on MAPK and PI3K/AKT pathways, as well as on the balance between pro-death and pro-survival factors, our compound may be used to interfere with oncogene expression in melanoma cells." (PMID 31635389, 2019). "In melanoma cells (A375 and H1205-lu), the expression of MMP9 and AMPK decreased in A375 cells after stimulation with IL-10 (20 ng/mL), while BCL-2 did not change significantly." (PMID 35893303, 2022). "As single agents, the BH3 mimetics S63845 (MCL1i), A1331852 (BCLXL inhibitor), and ABT-263 (inhibitor of BCL2, BCLXL, and BCLW) were not universally effective in suppressing cell growth in our melanoma cell line panel." (PMID 34451846, 2021). "Considering that anti-apoptotic Bcl-2 proteins were and are evaluated as prospective therapeutic targets in melanoma, it is surprising that the role of BCL2L10 in melanoma has never been studied." (PMID 33396645, 2020). "Our in vitro and in vivo data showed that the simultaneous targeting of BCL2 and MCL1 is effective in treating advanced melanoma, and this combination is more potent in melanomas without the BRAF-V600E/K variant." (PMID 32764384, 2020). "Many studies, including ours, have shown that targeting single anti-apoptotic BCL-2 family members is not sufficient to treat melanoma, and that targeting both MCL-1 and BCL-2 is needed to eliminate the MIC population." (PMID 27086916, 2017). "In melanoma, the NOXA/MCL-1/BCL-2 apoptotic node has emerged as a common vulnerable spot for targeting the MIC and non-MIC populations of melanoma." (PMID 27829238, 2016). "It is interesting to note that the expression of the anti-apoptotic protein BCL-2 was unexpectedly decreased in Mel8-I and Mel29-I resistant cells, suggesting that BCL-2 enhances rather than reduces chemosensitivity in melanoma cells." (PMID 27175588, 2016). "It is known that elimination of TFAP2A from non-metastatic primary melanoma cells increases their malignancy while re-expression abrogates it, by controlling transcription of genes such as MCAM-MUC18, MMP2, PAR1, VEGF, BCL2, CDKN1A/p21, E-cadherin and KIT." (PMID 25650662, 2015).